FOXO3 (forkhead box O3)
Diseases named in the same sentence as FOXO3 in open-access papers (continued):
Sharing a sentence is not in itself a finding about the gene and the disease.
chronic lymphoid leukemia (2 papers, 2013 to 2025). "More recently, it was demonstrated that a constitutively active mutant of the transcription factor FOXO3 fused to the TAT domain induced apoptosis in leukemic cell lines and reduced viability of primary chronic lymphoid leukemia (CLL) cells." (PMID 23865046, 2013).
chronic periodontitis (2 papers, 2025 to 2026). A chronic inflammatory process that affects the tissues that surround and support the teeth. "Downregulation of tumor suppressor genes including IRF1, LDOC1, and FOXO3 was also evident in tissues from patients with chronic periodontitis." (PMID 40924302, 2025).
diabetic neuropathy (2 papers, 2018 to 2024). A chronic, pathological complication associated with diabetes mellitus, where nerve damages are incurred due to diabetic microvascular injury involving small blood vessels that supply these nerves, resulting in peripheral and/or autonomic nerve dysfunction. "In addition, ILG mimics the effects of PGC-1α-mediated mitochondrial biogenesis, calorie restriction, 5′ AMP-activated protein kinase (AMPK)–mediated autophagy and Forkhead box O3a (FOXO3a) mediated stress resistance to counteract experimental diabetic neuropathy." (PMID 30443212, 2018).
epilepsy (2 papers, 2019 to 2023). A brain disorder characterized by episodes of abnormally increased neuronal discharge resulting in transient episodes of sensory or motor neurological dysfunction, or psychic dysfunction. "Therefore, higher expression of FOXO3 and associated activation of autophagy in epilepsy might be a compensatory mechanism to mitigate oxidative stress and linked neuronal injury." (PMID 37880579, 2023). "In vitro study demonstrated that a purified mitochondrial fraction from animal and human brains mainly in hippocampal neurons contains a large concentration of FOXO3 in response to epilepsy." (PMID 37880579, 2023). "A recent study suggests that the ketogenic diet could be highly effective in the management of resistance epilepsy through the modulation of neurotransmitters and induction of FOXO3 and autophagy." (PMID 37880579, 2023).
Ewing sarcoma (2 papers, 2020 to 2023). A small round cell tumor that lacks morphologic, immunohistochemical, and electron microscopic evidence of neuroectodermal differentiation. "FOXO1 has been described as a key regulator of Ewing’s sarcoma, but the role of FOXO3 is less clear." (PMID 37242535, 2023). "Preliminary studies showed that FOXO3 may also be a key regulator of Ewing’s sarcoma as well as a prognostic marker of uterine sarcoma." (PMID 37242535, 2023).
gallbladder cancer (2 papers, 2022 to 2023). "A recent study has shown that activation of FOXO3 by polyphyllin I induced apoptosis in human gallbladder cancer cells." (PMID 35207737, 2022). "We showed that AZD1480 induced apoptosis via regulation of JAK2/FOXO3 pathway in human gallbladder cancer SNU308 cells." (PMID 35207737, 2022). "Therefore, in this study, we tried to investigate the involvement of JAK2/FOXO3 pathway as one of down-stream signaling pathway in gallbladder cancer cells." (PMID 35207737, 2022). "Another study demonstrated that ratio of phosphorylated and total FOXO3 could be an important prognostic marker of tumor recurrence in patients with gallbladder cancer." (PMID 35207737, 2022). "Several studies investigated the relationship between FOXO3 and gallbladder cancers." (PMID 35207737, 2022). "Additionally, it was reported that FOXO3 expression could play a pivotal role in prognosis of gallbladder cancer." (PMID 35207737, 2022).
infarction (2 papers, 2017 to 2022). A localised pathological necrosis of tissue resulting from obstruction of the blood supply usually by a thrombus, an embolus, or vascular torsion. "Long-term and moderate exercise (75% of VO2max for 6 weeks) before infarction injury has also been shown to increase FOXO3 and its two downstream targets, MnSOD, and catalase, compared to sedentary rats with infarction." (PMID 36036015, 2022).
intracerebral haemorrhage (2 papers, 2024). "Studies on animal models have shown miR-144 to have a protective role against neuroinflammation and oxidative stress by targeting the pathway of miR-451-14-3-3ζ-FoxO3 in intracerebral hemorrhage." (PMID 39407977, 2024).
kidney (2 papers, 2013 to 2021). "miR-942-5p regulates septic acute kidney injury by targeting FOXO3." (PMID 34322152, 2021).
leiomyoma (2 papers, 2021 to 2024). A well-circumscribed benign smooth muscle neoplasm characterized by the presence of spindle cells with cigar-shaped nuclei, interlacing fascicles, and a whorled pattern. "Furthermore, both FOXO3 and PDCD4 are increased in leiomyoma compared with myometrial tissue." (PMID 33575847, 2021).
multiple sclerosis (2 papers, 2017 to 2023). A progressive autoimmune disorder affecting the central nervous system resulting in demyelination. "Its overexpression is also related to T helper cell differentiation in multiple sclerosis, possibly by a mechanism involving SMAD2, GATA3, and FOXO3 genes, whose participation in Th17 cell differentiation, Treg inhibition, and/or other T helper pathways has been underlined." (PMID 29349090, 2017).
muscle disorders (2 papers, 2023 to 2024). "Since we hypothesize an upregulation of Foxo3 to be related to muscle disorders, we aimed for a technical Foxo3 knockdown." (PMID 37681900, 2023).
myeloid malignancies (2 papers, 2016 to 2021). "The larger population of myeloid cells in FoxO3-deficient MYC10 mice is likely to be a significant factor contributing to accelerated myeloid tumour formation in this model." (PMID 26764572, 2016). "As the MYC10 and FoxO3−/−MYC10 mice are predisposed to myeloid tumours, we analysed the cell cycle profiles of bone marrow macrophages and granulocytes from healthy young mice." (PMID 26764572, 2016).
ovarian tumor (2 papers, 2020 to 2022). "Interestingly, activation of FOXO3 nuclear localization and consequent inhibition of the expressions of stemness markers, including Nanog, Oct4, and c-MYC, are caused by inhibition of the formation of ovarian tumor spheroids." (PMID 32899775, 2020). "In xenografted ovarian tumors, ARHI1 expression induces autophagy by inhibiting the PI3K/AKT/mTOR pathway and supporting nuclear localization of the transcription factor EB (TFEB) and Forkhead box O3 (FOXO3a), which in turn mediate the expression of crucial autophagy effectors." (PMID 35158815, 2022).
pneumonia (2 papers, 2022 to 2023). An acute, acute and chronic, or chronic inflammation focally or diffusely affecting the lung parenchyma, caused by an infection in one or both of the lungs (by bacteria, viruses, fungi, or mycoplasma.). "As a key regulator downstream of the PI3K-Akt signaling pathway, FoxO3 plays a key role in the regulation of pneumonia response and antioxidant genes." (PMID 38133396, 2023).
prostate tumor (2 papers, 2016 to 2024). "The docetaxel potential in prostate tumor therapy increases upon upregulation of circ-Foxo3 and is related to Foxo3 and EMT suppression, thereby reducing the malignancy of cancer cells." (PMID 38733529, 2024).
Salmonella Infections (2 papers, 2018 to 2023). Infections with bacteria of the genus SALMONELLA. "The signalling adapter molecule IKBKB was significantly upregulated in Kashmir favorella after Salmonella infection that showed its influence on FOXO3 expression as well." (PMID 37098463, 2023). "The protein–protein interaction (PPI) and protein-TF interaction network by STRINGDB analysis suggests that FOXO3 is a hub gene in the network and is closely related to Salmonella infection along with NF-κB1." (PMID 37098463, 2023). "The protein–protein interaction (PPI) and protein -TF interaction networks by STRINGDB analysis suggests that FOXO3 was hub gene in the network and closely related in Salmonella infection with NF-κB1." (PMID 37098463, 2023). "FOXO3, a transcriptional activator, is the potential marker of host resistance in Salmonella infection." (PMID 37098463, 2023). "The protein–protein and protein-TFs interaction analysis suggests that FOXO3 (Degree = 23 after thresholds) was hub gene in the network and closely related in Salmonella infection with NF-κB1, which is in accordance with the RNA-Seq and q-PCR results." (PMID 37098463, 2023). "FOXO3 serves as a marker of host resistance to Salmonella infection." (PMID 37098463, 2023).
T-cell lymphoma (2 papers, 2015 to 2020). "Moreover, analysis of expression profiling data from selected ALCL (GSE19069) and peripheral T-cell lymphoma patients (GSE6338) showed correlated activities of HHEX, CASP8, FOXO3 and BHLHE40, supporting this regulatory connection." (PMID 32922661, 2020).
thalassemia (2 papers, 2019 to 2022). An inherited blood disorder characterized by a decreased synthesis of one of the polypeptide chains that form hemoglobin. "However, the associated function of APOD with these signaling molecules, including AKT, JNK, and FOXO3, has not been studied in thalassemia." (PMID 30813444, 2019).
Ureteral obstruction (2 papers, 2019 to 2021). Obstruction of the flow of urine through the ureter. "FOXO3 was discovered to be activated in mice with unilateral ureteral obstruction." (PMID 35004893, 2021).
adenovirus infection (1 paper, 2019). "Overexpression of FoxO3 was achieved by adenovirus infection of HepG2 cells and was confirmed by western blotting." (PMID 31729980, 2019).
amyloid (1 paper, 2021). "Our study of FoxO3 in the 5xFAD mouse model supports a beneficial role of astrocytic FoxO3 against the amyloid pathology." (PMID 34727995, 2021).
autoimmune uveitis (1 paper, 2020). An autoimmune form of uveitis (disease). "In addition to the roles in the granulocytes, Mir223 has been known to be functional particularly in CD4+Th17 cells, which exacerbated the experimental autoimmune uveitis (EAU) by promoting autoreactive Th17 cell responses by inhibiting transcription factor FOXO3 expression." (PMID 33574820, 2020).
benign salivary gland tumors (1 paper, 2023). "This research revealed that the FOXO3 and MAPK1 genes are present in benign salivary gland tumors and also indicated a role of these genes in the development of benign salivary gland tumors." (PMID 38202222, 2023). "This research revealed that FOXO3 and MAPK1 are presence in the salivary gland tissue and in benign salivary gland tumors and also indicated a role of these genes in the development of pleomorphic adenomas." (PMID 38202222, 2023).
childhood cancer (1 paper, 2017). "To analyze whether FOXO3 contributes to drug-resistance in this childhood cancer, we investigated how different high-stage-derived NB cells respond to the activation of an ectopic FOXO3 allele." (PMID 28869600, 2017).
childhood leukemia (1 paper, 2013). An acute or chronic leukemia that occurs during childhood. "We uncovered, that FOXO3 activates apoptosis by induction of TRAIL and Noxa and found that the expression of the frequently mutated tumor suppressor p16INK4A in T-ALL represses endogenous FOXO3, suggesting that these two tumor suppressor proteins cooperate to prevent childhood leukemia." (PMID 23828551, 2013).
co-infection (1 paper, 2023). "Further, this FoxO3-induced stimulation of MuRF-1 was completely reversed with Ad-Smad3 co-infection." (PMID 37693008, 2023).
colorectal adenoma (1 paper, 2025). An adenoma that arises from the colon or rectum. "We found that the key components of sirtuin pathway, Sirtuin 1 (Sirt1) and forkhead box O3 (FOXO3), are significantly associated with the YAP gene in promoting colorectal adenomas." (PMID 39977302, 2025).
congenital toxoplasmosis (1 paper, 2025). Toxoplasma infection that is present from birth. "Further investigation using ex vivo human placental models combined with experimental models of congenital toxoplasmosis in mice deficient for Foxo3 and Foxo1 in the uterine compartment will help shed light on this matter." (PMID 41450565, 2025).
corneal diseases (1 paper, 2024). "To further explore the role of ZNF281 and FOXO3, we analyzed their expression changes in other corneal diseases." (PMID 39254179, 2024).
corneal ulcer (1 paper, 2019). Area of epithelial tissue loss from corneal surface; associated with inflammatory cells in the cornea and anterior chamber. "It is possible that one of important mechanisms of corneal ulcer reduction might be related to downregulation of inflammatory cytokines, especially TNFα and NF-ḳB, and the increased expression of FOXO3 induced by SAHA application." (PMID 31285488, 2019).
deafness (1 paper, 2015). An inherited or acquired condition characterized by the complete loss of the ability to hear from one or both ears. "The locus contained FOXO3 and SOBP, known to cause deafness in mice, but Sanger sequencing and careful assessment did not identify any variation in these genes." (PMID 26197441, 2015).
developmental delay (1 paper, 2021). "FOXO1, FOXO3, and FOXO4 proteins are localized in the cytoplasm during embryo development and are located in the nucleus in embryos with developmental delay." (PMID 33540675, 2021).
diabetic ketoacidosis (1 paper, 2020). The metabolic condition resulted from uncontrolled diabetes mellitus, in which the shift of acid-base status of the body toward the acid side because of loss of base or retention of acids other than carbonic acid is accompanied by the accumulation of ketone bodies in body tissues and fluids. "Stratification of the T1DM group according to the presence of initial diabetic ketoacidosis (DKA) did not indicate differences in FOXO3 expression in patients with DKA compared to a mild T1DM onset (P > 0.05)." (PMID 32851102, 2020).
dry eyes (1 paper, 2023). "In contrast to this, treatment of cornea epithelial cells with pro-inflammatory cytokines and tears from patients with DED revealed a nuclear localized FOXO3, suggesting an impairment in corneal epithelial homeostasis in the dry eye condition." (PMID 37153108, 2023). "Interestingly, co-treatment of cells incubated with tears from dry eyes and lacritin reversed the nuclear localization of FOXO3, sequestering it in the cytosol." (PMID 37153108, 2023).
follicular lymphoma (1 paper, 2023). Follicular lymphoma is a form of non-Hodgkin lymphoma characterized by a proliferation of B cells whose nodular structure of follicular architecture is preserved. "SESN1 is co-regulated with FOXO3 and is a target of the EZH2Y641X gain of function mutation and of focal deletions in follicular lymphoma." (PMID 36670235, 2023).
gout (1 paper, 2019). A condition characterized by painful swelling of the joints, which is caused by deposition of urate crystals. "Further support for the role of the ILS pathway in modulating UA metabolism stems from a human candidate gene study identifying SNPs in the ILS genes AKT2 and FOXO3 being associated with serum UA levels or gout." (PMID 31415568, 2019).
granulosa cell tumor (1 paper, 2018). A slow-growing, malignant tumor, characterize by the presence of granulosa-like cells and Call-Exner bodies, that is almost always found in the ovary. "For instance, when Foxo1 and Foxo3 genes were selectively inactivated follicle development is impaired and granulosa cell tumor formation is increased in a mouse model." (PMID 29549247, 2018). "Emerging data from animal studies suggest that Forkhead box O3 (FOXO3), phosphatase and tensin homolog (PTEN) and mammalian target of rapamycin (mTOR) pathways converge on the same follicle dormancy and granulosa cell tumor formation phenotypes." (PMID 29549247, 2018).
hemochromatosis (1 paper, 2017). A disorder of iron metabolism characterized by a triad of HEMOSIDEROSIS; LIVER CIRRHOSIS; and DIABETES MELLITUS. "Rs1853021 in LPA and rs2802292 in FOXO3 (p = 0.052) and rs1800562 in HFE (hemochromatosis) and rs56354395 in ADIPOQ (adiponectin, C1Q and collagen domain containing) (p = 0.059)." (PMID 28206976, 2017).
hemoglobinopathies (1 paper, 2015). "As FOXO3 activity is critical for the correct temporal gene expression in maturing erythroblasts, we predict that abnormal FOXO3 expression/function may significantly influence erythroid disorders as has been reported specifically for hemoglobinopathies." (PMID 26452208, 2015).
hypertrophic cardiomyopathy (1 paper, 2024). A condition in which the myocardium is hypertrophied without an obvious cause. "FOXO3 was found to be up-regulated in cardiac fibroblasts for both Dilated and hypertrophic cardiomyopathy." (PMID 39202774, 2024).
hyperuricemia (1 paper, 2024). An abnormally high level of uric acid. "In a mouse model of hyperuricemia after drug intervention, it was found that reducing uric acid was accompanied by upregulation of FOXO3 protein expression and changes of glutathione peroxidase levels." (PMID 38957396, 2024). "We found that FOXO3, Nrf2, NQO1, Gpx4 and PIK3CA are not only related to regulating metabolic diseases, but also may have therapeutic effects on aging, cancer, or hyperuricemia." (PMID 38957396, 2024). "It is suggested that the regulation of FOXO3 and GPx4 may be related to the therapeutic mechanism of improving hyperuricemia, but there is no clinical evidence to prove it." (PMID 38957396, 2024).
Impaired glucose tolerance (1 paper, 2019). An abnormal resistance to glucose, i.e., a reduction in the ability to maintain glucose levels in the blood stream within normal limits following oral or intravenous administration of glucose. "In vivo, FoxO3 gain of function prompted hepatic TG deposition and impaired glucose tolerance on a chow diet, and those impacts were further enhanced when fed a high-fat diet." (PMID 31729980, 2019).
insomnia (1 paper, 2025). A sleep disorder characterized by difficulty in falling asleep and/or remaining asleep. "Furthermore, the use of conditional FOXO3-knockout mice would provide a more direct means to validate the role of the axis in insomnia-related phenotypes, neurotransmitter levels, and cellular gene expression." (PMID 41305549, 2025).
keratoconus (1 paper, 2024). A degenerative, structural disorder of the eye, characterized by a cone-shaped protrusion of the cornea. "We investigated the role of ZNF281 and FOXO3 using single‐cell transcriptomic datasets from human keratoconus corneas, a disease characterized by decreased antioxidant capacity." (PMID 39254179, 2024). "We found downregulation of ZNF281 and FOXO3, along with most of their targeted antioxidant genes in keratoconus corneas, suggesting that the dysregulation of the antioxidant programs mediated by ZNF281 and FOXO3 may be involved in the development of keratoconus." (PMID 39254179, 2024).
laminopathies (1 paper, 2023). "Albeit with this finding, FOXO3 was proven bona fide as an effective target for repressing myocardial cell apoptosis of the familial DCM identified in laminopathies." (PMID 37138538, 2023). "Nonetheless, a recent study on a mouse model of laminopathies pointed out that suppression of cardiac FOXO3 improved myocardial cell apoptosis and partially rescued DCM phenotypes of the laminopathies." (PMID 37138538, 2023).
left ventricular hypertrophy (1 paper, 2023). Enlargement of the LEFT VENTRICLE of the heart. "The protein kinase B (AKT)/FOXO3 and AKT/mammalian target of rapamycin (mTOR) pathways have been implicated as potential mechanisms involved in the regulation of left ventricular hypertrophy (LVH) induced by pressure overload." (PMID 38074330, 2023).
leprosy (1 paper, 2018). Leprosy is a chronic infectious disease affecting primarily the skin and peripheral nervous system.
lumbar disc herniation (1 paper, 2022). "Clinical tissue samples were collected from patients with lumbar disc herniation (LDH), in which the expression of p300, forkhead box O3 (FOXO3), and sirtuin 1 (Sirt1) was determined." (PMID 35907249, 2022).